RAG2 (recombination activating 2)
Diseases named in the same sentence as RAG2 in open-access papers (continued):
Sharing a sentence is not in itself a finding about the gene and the disease.
RAG2 also shares sentences with these, for which no sentence is quoted: combined immunodeficiency (9 papers); DiGeorge syndrome (3); vasculitis (3); acute myeloid leukemia (2); dermatitis (2); Insulin resistance (2); pneumonia (2); acute liver failure (1); adenocarcinoma (1); adenoma (1); AIDS (1); Alzheimer disease (1); amyotrophic lateral sclerosis (1); Ataxia (1); ataxia telangiectasia (1); autoimmune polyendocrinopathy syndrome type 1 (1); B cell deficiency (1); bladder tumors (1); Bloom syndrome (1); bone marrow failure (1); brain cancer (1); bronchiolitis (1); bronchitis (1); Burkitt lymphoma (1); cardiomyopathy (1); cartilage disease (1); Cernunnos deficiency (1); cervical cancer (1); common variable immunodeficiency (1); Crohn disease (1).
A further 49 diseases each share a sentence with RAG2 in 1 paper.